PCNA (proliferating cell nuclear antigen)
Diseases named in the same sentence as PCNA in open-access papers (continued):
Sharing a sentence is not in itself a finding about the gene and the disease.
tumor (continued). "To answer this question, we measured the proliferative activity of tumor cells by staining tumor tissue sections isolated from different animal groups with anti- Ki67 and anti-PCNA markers." (PMID 33596850, 2021). "In vivo, during tumour formation, the expression of Ki‐67 and proliferating cell nuclear antigen (PCNA) in the tumour tissue with HIF‐1α KO fibroblasts was significantly lower than that of normal fibroblasts." (PMID 33943003, 2021). "In conclusion, miR-340 functions as a tumor suppressor of BC, which inhibited proliferation and induced apoptosis by targeting Glut-1 partly through regulating PCNA, Bax expression and PI3K/AKT pathway." (PMID 34861846, 2021). "The fluorescence signal of PCNA and Ki67 were significantly decreased in tumor tissues from CPNE3 knock-down group." (PMID 35003348, 2021). "Western blot analysis confirmed that combined treatment significantly reduced the expression levels of RAGE, p-STAT3, STAT3, p-AKT, and PCNA in tumor tissues compared to the PT or CQ monotherapy groups." (PMID 34771150, 2021). "A tumor analysis revealed that obese cKO mice attenuated inflammatory areas, PCNA, and F4/80 compared to obese WT mice, indicating a reduced tumor burden, and there were positive relationships between the ascites and tumor parameters." (PMID 34638514, 2021). "Consistent with the decreased tumor growth, PCNA, a biomarker of proliferation, and p-ERK staining were also reduced in tumors in mice treated with MSU42011." (PMID 34638488, 2021). "Pan-cancer analysis demonstrated that dysregulated expression of PCNA was highest in CC among 24 other tumor types." (PMID 34900731, 2021). "In recent, similar anti-cancer effects of AS-IV were reported including blocking of MAPK signal, decreased PCNA and Ki67 expression, and trigging G1 arrest in tumor cell." (PMID 34068164, 2021). "The PCNA staining of tumor tissues followed a similar tendency and presented a significantly lower proliferation index in the 3BP@PLGA-IR780 + Laser group." (PMID 34930284, 2021). "This review discusses the recent studies about the PTMs in regulating PCNA functions and the implications in tumor development." (PMID 34671219, 2021). "Further, PCNA is expressed at high levels in peritumoral tissue in U251 tumors indicative of proliferative cells outside of the demarcated tumor boundary in the peritumoral area." (PMID 34513675, 2021). "Examination of clinical tumor tissues using IHC also proved that the expression of RCN1 was positively correlated with that of PCNA (n = 68)." (PMID 34663798, 2021). "Immunohistochemical analysis of tumor tissues showed that NHWD-870 combined with cisplatin more effectively inhibited the expression of the tumor proliferative antigen PCNA." (PMID 34168981, 2021). "While both U87 and U251 are positive for PCNA, as validated with IHC, U251 has much greater proliferation at the tumor margin." (PMID 34513675, 2021). "Ki67 and PCNA expression levels were lower in mouse tumour tissues in the ADFP knock‐down NCI‐H1299 group and higher in those of the ADFP‐overexpressing NCI‐H1299 group." (PMID 33249703, 2021). "Next, we detected the positive rates of Ki67 and PCNA in the tumor tissues from the subcutaneous xenograft models by immunohistochemistry." (PMID 33767587, 2021). "After 11-KT treatment, the PCNA-positive cells increased significantly in male MXs + Dox, indicating that 11-KT boosted tumor growth." (PMID 34943942, 2021). "IHC analysis of Ki67 and PCNA in tumor tissues revealed that proliferation was markedly reduced in the MYDGF knockdown group (p < 0.05)." (PMID 33391471, 2021). "The U87 MG and PBT24 cell line tumors study shows the effect the U87 and PBT24 tumor differences have on the impact of varying NaDCA concentrations on tumor growth, and on the PCNA and EZH2 expression in the tumor cell." (PMID 33716589, 2021). "The IHC staining results showed that the staining intensity of KI67 and PCNA in the tumor tissues was significantly decreased after ELM treatment." (PMID 34540820, 2021).
tumor (continued). "Immunofluorescence staining was performed to detect the expression of PCNA, Ki67 in the xenograft tumor tissues." (PMID 35003348, 2021). "In comparison to tumor cells from the PT, in CTCs the expression levels of PCNA and MKI67 was reduced 495.5-fold (p-value 0.0008, two-tailed t-test) and 81.9-fold (p-value 0.0054, two-tailed t-test), respectively." (PMID 34885114, 2021). "Proliferating cell nuclear antigen (PCNA), as a excellent indicator of cells proliferation, has been reported to be markers of tumour cells." (PMID 33544460, 2021). "HE staining and IHC analysis of PCNA in the xenograft tumor tissue demonstrated the suppression of tumor cell proliferation by inhibitor of miRNA-30b-5p." (PMID 33390177, 2021). "Immunohistochemical analysis of PCNA in tumor samples demonstrated that the combination of aspirin and berbamine more significantly inhibited cancer cell proliferation than single-agent." (PMID 33917483, 2021). "There was a significant reduction in tumor proliferation, as well as a reduction in crypt cells marked by PCNA staining." (PMID 33767225, 2021). "Accordingly, as shown by immunofluorescence analysis performed on tumours at day 35, the expression levels of proliferating cell nuclear antigen (PCNA) strongly decreased only in combination group compared to single treatments and untreated animals." (PMID 34784956, 2021). "(F) The density of proliferating cell nuclear antigen (PCNA)-positive cells in the tumor tissues of AOM/DSS-treated OxtCre and OxtCre;DTA mice." (PMID 34528509, 2021). "IHC analysis found a decrease of Ki-67 and PCNA expression in xenograft tumor tissues with THAP9-AS1 knockdown compared to the sh-NC group." (PMID 33854048, 2021). "Overexpression of γ-tubulin was widespread in poorly differentiated, proliferating tumor cells stained for PCNA (proliferating cell nuclear antigen) but was significantly diminished in quiescent differentiating tumor cells undergoing neuritogenesis." (PMID 34830792, 2021). "Consistent with tumor inhibition, HT also decreased cell proliferation, which was observed through the reduction of PCNA expression." (PMID 33986437, 2021). "There was significant lower number of PCNA-positive cells in SW1990-LNC-KD cell xenograft tumor tissue (p<0.01)." (PMID 34395245, 2021). "In agreement with the reduction in tumor size, the number of proliferating cells, revealed by the immunostaining for PCNA, was significantly decreased in hM3Dq AAV-injected mice compared with the controls." (PMID 34528509, 2021). "Western blot result uncovered that Ki67, MMP-9, MMP-2, PCNA and other tumor markers were prominently activated after the downregulation of ADAMTS9-AS1, indicating increased tumor proliferative activity." (PMID 34900984, 2021). "As expected, Nur77 shRNA strongly inhibited subcutaneous tumor formation and reduced PCNA expression, a cell proliferative marker, in xenograft tumors." (PMID 33537093, 2021). "NaDCA impact on U87 MG and PBT24 tumor on proliferating cell nunclear antigen (PCNA) and enhancer of zeste homolog 2 (EZH2) expression in the tumor was different, depending on the NaDCA dose." (PMID 33716589, 2021). "Immunohistochemical staining revealed that Ki-67 and PCNA levels were decreased in tumor tissues from chidamide treated mice." (PMID 34926293, 2021). "To mechanistically explain our observations, we also investigated the effect of TCS treatment on markers of tumor proliferation (Ki67, PCNA)." (PMID 33750370, 2021). "(G and H) Immunohistochemical staining for proliferating cell nuclear antigen (PCNA) of tumor tissue." (PMID 34528509, 2021).
tumor (continued). "PT was continuously administered orally via the diet at a concentration of 40 ppm for 45 weeks and resulted in reduced tumor multiplicity and downregulated the expression of proliferating cell nuclear antigen (PCNA), β-catenin and cyclin D1." (PMID 33801098, 2021). "Because proliferating the cell nuclear antigen (PCNA) was a universal marker of proliferating cells, we evaluated PCNA positive cells in omental tumor tissues." (PMID 34638514, 2021). "It is known that PCNA is overexpressed in tumour cells, to adapt the high capacity of such cells to exhibit an uncontrolled replication." (PMID 33536086, 2021). "Immunostaining of tissue section with PCNA demonstrated large numbers of actively proliferating tumor cells in the untreated group at 24 h post-treatment." (PMID 33986437, 2021). "We further performed western blotting to detect the protein expression of JWA, CDK12, Bcl-2, BAX, Caspase-3, and PCNA in xenograft tumor tissues." (PMID 34686673, 2021). "PCNA was an auxiliary protein involved in DNA replication and has been confirmed to be an indicator to evaluate the proliferation status of tumor cells." (PMID 34544452, 2021). "IHC staining of xenograft tumor specimens showed that the expression levels of Ki-67 (p = 0.0087) and PCNA (p = 0.0049) in Chidamide-treated group was lower than in control group." (PMID 33192510, 2020). "The increased effect of PRDX6 was further verified by growth markers, including PCNA, in tumor tissues." (PMID 32201510, 2020). "Consistent with its effects in vitro, CPX increased the tumor proliferative index compared to 0.9% NaCl treatment as determined by IHC for PCNA and Ki-67, respectively." (PMID 32719342, 2020). "On the other hand, the expression of total and nuclear FAK, EZH2, and PCNA significantly inversely correlated with tumor size." (PMID 32806748, 2020). "KIAA0101 functions by binding to PCNA, an essential scaffold molecule for DNA repair, replication, cell proliferation and tumor invasion." (PMID 32855364, 2020). "Considering the drug effect in tumor tissues, we conducted histological analysis by using two proliferation markers: PCNA and Ki67, and TUNEL staining for cell apoptosis detection." (PMID 32024821, 2020). "Confirming that tumor abundance in FF injected liver represented accelerated cancer cell replication, proliferating cell nuclear antigen (PCNA) was increased." (PMID 32879136, 2020). "Quantification for IGF1R/PCNA PLA signals was carried out by manually counting 100 tumor cells in at least three different randomly selected areas of the tumor." (PMID 32701997, 2020). "Both tumor weight and PCNA staining further confirmed the inhibitory effects by LINC01426 silencing." (PMID 32699526, 2020). "The IHC analysis of PCNA and Ki67 also indicated that the proliferative capacity of tumor was inhibited after luteolin treatment or THOC1 knockdown." (PMID 32669125, 2020). "CircMRPS35 knockdown by shRNA lentivirus in MGC803 increased tumor growth, tumor weight and the expression of Ki-67 and PCNA." (PMID 32164722, 2020). "PCNA levels are directly correlated with malignancy and tumor invasion, vascular infiltration, and survival." (PMID 33327620, 2020). "PCNA is a specific nucleic acid protein that exists in all phases of the proliferation cycle of normal and tumor cells." (PMID 33163082, 2020). "It has been reported in the literature that AKT and STAT3 have also been identified to be involved in the regulation of downstream factors, including PCNA, Bcl2 and CyclinD1, and to manage tumor proliferation and apoptosis." (PMID 32463472, 2020). "In mouse model, the inhibition of growth, increased apoptosis, and decreased expression of proliferating cell nuclear antigen (PCNA) was observed in MDA-MB-231 tumor xenograft mouse model." (PMID 36046777, 2020). "Next, we detected the proliferative marker PCNA for tumor growth using immunohistochemistry analysis." (PMID 32530032, 2020).
tumor (continued). "Immunohistochemical staining for proliferating cell nuclear antigen (PCNA) showed that both F-AgÅPs and cisplatin markedly repressed cell proliferation in the tumor sites, but the inhibitory effects of F-AgÅPs were much higher than that of cisplatin." (PMID 32685015, 2020). "Both nuclear and cytoplasmic IGF1R/PCNA colocalization signals were observed at varying levels in tumor tissue." (PMID 32701997, 2020). "IGF1R/PCNA colocalization was more frequently increased in tumor cells than in adjacent normal, and more prominent in areas with dysplasia and invasion." (PMID 32701997, 2020). "In summary, we have shown that GAS7, a direct downstream target of miR-362-5p, can exert its tumor suppressive functions in THP-1 cells through regulation of PCNA, CDK4, cyclin D1, and p21." (PMID 31925702, 2020). "PCNA staining demonstrated a stronger ability of F-AgÅPs to suppress cell proliferation in the tumor sites compared with cisplatin." (PMID 32685015, 2020). "Intriguingly, the protein expression of FAK, EZH2, and PCNA significantly inversely correlated with tumor size." (PMID 32806748, 2020). "After 30 days of implantation, 8 out of the 9 mice injected with U87-miR-4310 cells had larger tumor burdens and displayed higher expression of Ki67 and proliferating cell nuclear antigen (PCNA) in tumor tissues relative to controls." (PMID 33327965, 2020). "In this study, the decreased expression of thee PCNA indicated that the petroleum ether extract of C. minax effectively reduced tumor cell DNA synthesis, thus resulting in the inhibition effect on tumor cell proliferation." (PMID 33163082, 2020). "The stathmin signature correlated with stathmin mRNA expression (p < 0.001) and strongly with two tumour cell proliferation scores (Oncotype Dx and the PCNA score; both p < 0.001)." (PMID 32076022, 2020). "In transwell co-culturing assays, we found that co-culturing HepG2 or Huh7-tumor cells with LX2-stellate cells significantly increased PCNA-mRNA-expression in HepG2 and Huh7-tumor cell lines." (PMID 33103995, 2020). "Quantification of PCNA-positive cells by field exhibited a regorafenib reduction of tumor proliferation (377 ± 140), compared to vehicle-treated animals (563 ± 62) that was potently increased by A-1331852 co-administration (70 ± 73)." (PMID 32024199, 2020). "The results presented that a marked decrease in the numbers of Ki-67-positive (Ki-67+) cells and PCNA-positive (PCNA+) cells was observed in PRDX2-knockdown tumor tissues, indicating PRDX2 knockdown suppressed cell proliferation in vivo." (PMID 32908916, 2020). "IHC staining of brain sections from tumour‐bearing mice also demonstrated that EFV suppressed the expression of PCNA and induced protein levels of cleaved caspase‐3." (PMID 31777202, 2020). "IHC assay demonstrated that the expressions of Ki‐67 and PCNA (cell proliferation markers) were significantly down‐regulated in LINC00519‐silenced tumours." (PMID 32297697, 2020). "An immunohistochemical study showed that, through inhibiting the expression of the VEGF and growth of the tumor blood vessel, the proliferation of tumor cell and expression of PCNA can be inhibited." (PMID 33163082, 2020). "GSDME-mediated pyroptosis promotes the development of CAC by releasing HMGB1, which induces tumor cell proliferation and PCNA expression through the ERK1/2 pathway." (PMID 33160389, 2020). "Bcl-2 markedly decreased, leading to a dramatic increase in the Bax/Bcl-2 ratio in LAIR-1 overexpression tumor samples, while the expression levels of ki-67 and PCNA remained unchanged." (PMID 32628130, 2020). "It was found that proliferating cell nuclear antigen (PCNA), a proliferation-related marker in neoplasms, had its maximum expression peak in the S phase and G2 phase of the cell cycle." (PMID 32552851, 2020). "We measured tumor cell proliferation by determining the number of hepatic tumor cells that were positively immunostained for PCNA in the livers of mice from different groups." (PMID 32751728, 2020).
tumor (continued). "Immunohistochemistry was performed on tumor tissues, and interestingly, the results showed that the expression level of PCNA in the TIM- and TIPIN-knock down groups was significantly reduced, suggesting a marked inhibition of cell proliferation." (PMID 32499870, 2020). "There were fewer PCNA positive cells in siL21-Mix-treated tumors, suggesting that the proliferative activities of tumor cells were reduced significantly." (PMID 33014855, 2020). "Immunohistochemical analysis and immunofluorescence staining for cytokeratin 19, proliferating cell nuclear antigen, and α-smooth muscle actin were performed in tumor and peritumor liver tissues." (PMID 33008300, 2020). "Concomitant with the results, we also observed the decreased tumor proliferation by Chi3L1 and PCNA immunostaining." (PMID 31929760, 2020). "When comparing BBD24 with cisplatin, BBD24 was more effective in inhibiting tumor growth and PCNA expression." (PMID 32713851, 2020). "The Rad18/PCNA PLA signals sometimes appeared as massive signal clusters (>50 signals per nuclei) in individual tumor cells." (PMID 32701997, 2020). "After 15 days, mice injected with SUNE1-miR-4721 or HONE1-miR-4721 had higher tumor burdens and displayed elevated Ki-67 and proliferating cell nuclear antigen (PCNA) expression in the overexpressed (oe-)miR-4721 group relative to the negative control." (PMID 33230457, 2020). "Collectively, we proposed that PRDX1 promoted tumor cell proliferation probably through regulating Nanog and PCNA expression." (PMID 31956363, 2020). "In accordance with these findings, the tumor cells from the knockout mice had a higher expression of the proliferation markers PCNA, Cyclin D1 and CDK4." (PMID 33245729, 2020). "Immunohistochemical analyses revealed that the expression of GRP78 was significantly decreased in SHQ1-KD tumors.Tumor xenografts were stained with a PCNA antibody for detecting proliferation." (PMID 32522979, 2020). "IHC staining using PCNA as an indicator of tumor cell proliferation revealed the PCNA expression was substantially lower in the sh-MCM3 group compared with the control group." (PMID 32597491, 2020). "Tumor cell proliferation was evaluated by immunostaining for PCNA, and angiogenesis was evaluated by immunostaining for CD34." (PMID 32256354, 2020). "We therefore analysed the expression of the ER-regulated genes (ERGs) TFF1, GREB1 and PR, together with PLK1, Ki67, PCNA and CENPE (a centromere associated protein that accumulates in G2 phase and is involved in chromosome alignement), in treated tumours." (PMID 32792481, 2020). "Growth of shCSF2 tumours was significantly reduced relative to controls (shNeg), as shown by anti-PCNA immunofluorescence and histologic evaluation of the tumour volume." (PMID 32390004, 2020). "Further, we examined the expression of the PCNA that is generally defined as proliferation marker in tumor xenografts." (PMID 33014855, 2020). "The simultaneous staining of Collagen type I and PCNA allowed to delineate the tumor areas in the liver." (PMID 32872334, 2020). "The tumor size, tumor weight and PCNA expression were significantly impaired by Linc00337 depletion." (PMID 33054826, 2020). "IHC staining analysis of xenograft tumor paraffin-embedded specimens showed that the expression of Ki-67 (p = 0.025) and PCNA (p = 0.008) in the VPS9D1-AS1KD group was lower than that in the NC group." (PMID 33192510, 2020).